ACTG1 (actin gamma 1)
Diseases named in the same sentence as ACTG1 in open-access papers (continued):
Sharing a sentence is not in itself a finding about the gene and the disease.
esophageal squamous cell carcinoma (1 paper, 2020). Esophageal squamous cell carcinoma (ESCC) is a type of esophageal carcinoma (EC) that can affect any part of the esophagus, but is usually located in the upper or middle third. "Through screening, we found that the lncRNA Actin Gamma 1 Pseudogene (AGPG) is required for increased glycolysis activity and cell proliferation in esophageal squamous cell carcinoma (ESCC)." (PMID 32198345, 2020).
gall bladder cancer (1 paper, 2024). "As bio-informatic research has shown, ACTG1 was highly upregulated in gall bladder cancer and suggested to be used as a biomarker for the early stage of this type of cancer." (PMID 39000458, 2024).
heart failure (1 paper, 2025). Inability of the heart to pump blood at an adequate rate to meet tissue metabolic requirements. "The results showed that the expression levels of HIF-1α, IL10, PAD4, ACTG1, SOD2, and GAPDH were higher in heart failure patients with Qi deficiency and blood stasis syndrome compared to the HP group." (PMID 40671145, 2025).
HIV-1 infection (1 paper, 2019). The type species of lentivirus and the etiologic agent of acquired immunodeficiency syndrome (AIDS). "Additionally, ACTB and ACTG1 are known to inhibit viral assembly and production, and THBS1 is known to inhibit HIV-1 infection." (PMID 30626383, 2019).
influenza (1 paper, 2023). An acute viral infection of the respiratory tract, occurring in isolated cases, in epidemics, or in pandemics; it is caused by serologically different strains of viruses (influenzaviruses) designated A, B, and C, has a 3-day incubation period, and usually lasts for 3 to 10 days. "Additionally, genes involved in cell processes and cytoskeletal structural elements were upregulated in activated cTfh cells compared to resting cells following influenza vaccination: ELMO2, ACTG1, STMN1, ANP32B, UCP2, and HMGB3." (PMID 37063867, 2023).
lymph node metastasis (1 paper, 2023). "Other genes alternating in both primary tumors and lymph node metastasis tumors within individuals include CALR (Calreticulin), FRG1(FSHD Region Gene 1), and ACTG1 (Actin Gamma 1)." (PMID 36653483, 2023).
neuroblastoma (1 paper, 2025). Neuroblastoma (NB) is the most common solid, extracranial childhood tumor. "Seven of our hits (Tubb1, Tubb5, Eef1a1, Eef1g, Gapdh, Nudc, Actg1) are present in their list of 52 enriched proteins from TGM2 stimulated N2a neuroblastoma cells." (PMID 41142754, 2025).
pancreatic cancer (1 paper, 2023). "In addition, exosomal PGAM1 could bind to γ-actin (ACTG1), which promotes podosome formation and metastasis in pancreatic cancer." (PMID 38077434, 2023).
parasite (1 paper, 2024). "Expression profiles revealed significant downregulation of mRNA for proteins ENO1, ACTG1, TUBB, and TUBA3D at 3, 6, and 12 h post parasite infection, respectively." (PMID 38504274, 2024).
pemphigus vulgaris (1 paper, 2024). Pemphigus is a group of chronic autoimmune skin diseases characterized by blister formations on the outer layer of the skin and the mucous membranes. "The dysregulation of genes such as FGA, VWF, and ACTG1 suggests that alterations in their transcription and expression may contribute to the pathogenesis of pemphigus vulgaris." (PMID 39593117, 2024). "Among these genes, FGA, VWF, and ACTG1 were abnormally expressed, supporting the hypothesis that platelet activation may play an important role in the progression of pemphigus vulgaris." (PMID 39593117, 2024).
pulpitis (1 paper, 2023). Inflammation of the dental pulp. "Amongst the 22 modules, the darkgray module was determined as the most pivotal module for pulpitis, from which 5 core genes, A HMOX1, LOX, ACTG1, STAT3 and GNB5, were selected, and assumed to exert pivotal effects on the pathophysiologic causal links of pulpitis." (PMID 36593446, 2023). "Subsequently, the protein coding genes HMOX1, LOX, ACTG1, STAT3, GNB5 were selected as the core genes, as they were most negatively or positively correlated modules with pulpitis statistically." (PMID 36593446, 2023). "More in depth researches are needed to interrogate the effects of ACTG1 and GNB5 on pulpitis." (PMID 36593446, 2023). "However, to our knowledge ACTG1 and GNB5 have not been studied in pulpitis yet." (PMID 36593446, 2023).
sarcoma (1 paper, 2025). A usually aggressive malignant neoplasm of the soft tissue or bone. "Both ACTA1 and ACTG1 were highly expressed in the PLMS and high-grade sarcoma groups, with expression more pronounced in the latter." (PMID 40868997, 2025).
systemic lupus erythematosus (1 paper, 2020). An autoimmune multi-organ disease typically associated with vasculopathy and autoantibody production. "In the third trimester, systemic lupus erythematosus and proteasome were enriched in the acute disease while Fc gamma R-mediated phagocytosis (VAV1, MARCKSL1, WASF2, DNM2, HCK, MAP2K1 genes) and adherens junction (ACTG1, WASF2, SMAD4, CSNK2B, EP300 genes) represented the subclinical category." (PMID 32012176, 2020).
Tinnitus (1 paper, 2024). Tinnitus is an auditory perception that can be described as the experience of sound, in the ear or in the head, in the absence of external acoustic stimulation. "In fact, tinnitus and episodes of vertigo and/or dizziness have been reported in the literature in up to 50% of cases of patients with variants in the ACTG1 gene." (PMID 38592426, 2024).
uterine cancer (1 paper, 2020). Primary or metastatic malignant neoplasm involving the uterine corpus and/or the cervix. "Overall, further elucidating the tumorigenic role of ACTG1 gains in uterine cancers potentially identifies critical biology underlying the pathogenesis of uterine cancers." (PMID 33217970, 2020). "In this study, we found ACTG1 was associated with several dysregulated transcriptional profiles and features in uterine cancers." (PMID 33217970, 2020). "Overall, our results imply a need to develop functional uterine cancer models to study how ACTG1 protein levels modulate key biology and signaling pathways in 2D or even 3D models." (PMID 33217970, 2020). "Together, this data suggests that while ACTG1 gains occur more commonly in higher grade uterine cancers, they nonetheless remain prognostic for overall survival in this cohort." (PMID 33217970, 2020). "Further, ACTG1 was the only actomyosin gene that regulates the fitness of uterine cancer cell lines." (PMID 33217970, 2020). "In the preclinical setting, this also requires the perturbation of ACTG1 in models in which one can evaluate uterine cancer cell interaction with immune cells, such as immune-competent tumor-forming mouse models or co-culture models in vitro." (PMID 33217970, 2020). "While our observations confirm a functional role of ACTG1 in uterine cancers, the results also implicate ACTG1 expression is essential for the fitness of several other cancer lineages, including that of ovarian and lung." (PMID 33217970, 2020). "To identify common biology among all uterine cancer samples with ACTG1 gains, we performed GSEA in all the uterine tumors from the UCS and UCEC cohorts in The Cancer Immunome Atlas (TCIA)." (PMID 33217970, 2020). "Functionally, the CRISPR-CAS9 gene deletion of ACTG1 had the most robust and consistent effects in uterine cancer cells relative to 20 other lineages." (PMID 33217970, 2020). "Overall, we propose that ACTG1 regulates the fitness of uterine cancer cells by modulating cell-intrinsic properties and the tumor microenvironment." (PMID 33217970, 2020). "While mechanisms that target actin cytoskeleton genes are proposed forms of cancer therapeutics in other studies our findings indicate precision strategies against ACTG1 could yield benefits for a subset of uterine cancer patients with high-grade tumors." (PMID 33217970, 2020). "Overall, our analysis predicted potential regulatory roles for MYLK2 and ACTG1 in uterine cancers." (PMID 33217970, 2020). "However, whether ACTG1 is indeed a marker of uterine cancer response to immune therapies can only be determined once the genomics and transcriptomics of resistant patients are fully characterized from these clinical studies." (PMID 33217970, 2020). "Given that ACTG1 and MYLK2 showed the greatest alteration frequency in uterine cancer, we sought to explore them further within uterine cancer subtypes." (PMID 33217970, 2020). "Given that ACTG1 and MYLK2 amplifications or overexpression were consistently observed in uterine cancers, we sought to analyze their potential as uterine cancer biomarkers." (PMID 33217970, 2020). "In summary, the ACTG1 functions relative to other actomyosin genes support the notion that it is a potential biomarker and a target gene in uterine cancer precision therapies." (PMID 33217970, 2020). "Understanding how ACTG1 may affect PRC2 activity in the absence of these regulatory genes potentially elucidates novel mechanisms of PRC2 functions in uterine cancer." (PMID 33217970, 2020). "To determine potential mechanisms of ACTG1 and MYLK2 gains, we also examined genomic instability through measurements of fraction of the genome altered (FGA) in uterine cancers with and without ACTG1 and MYLK2 gains." (PMID 33217970, 2020).
uterine carcinosarcoma (1 paper, 2020). A usually aggressive malignant neoplasm arising from the uterine corpus and less often the cervix. "Uterine carcinosarcomas (UCS) were the lineage with the greatest rates of genomic or transcript upregulation of MYLK2 and ACTG1, with Net Gain Scores of 0.21 and 0.14 respectively." (PMID 33217970, 2020). "ACTG1 and MYLK2 were gained (amplified and/or overexpressed) at 5~14% and 5~20%, respectively, in uterine mixed endometrial carcinoma (UMEC), uterine serous carcinoma (USC), uterine endometrioid carcinoma (UEC) and uterine carcinosarcoma (UCS)." (PMID 33217970, 2020).
uterine tumors (1 paper, 2020). "Overall, these orthogonal approaches indicate uterine tumors with ACTG1 gains have repressed IFN-γ and lymphocyte infiltration, which suggests these tumors may exhibit differential responses towards innate immunity or even immunotherapies." (PMID 33217970, 2020).
viral myocarditis (1 paper, 2021). Myocarditis that is caused by an infection with a viral agent. "We found three genes (CASP8, ACTG1, and CCND1) that were significantly associated with viral myocarditis." (PMID 34722003, 2021).
virus infection (1 paper, 2017). "Meanwhile, only three proteins that displayed regulated expression in both H5N1-infected CEF cells at all the time points were ACTG1, LMNB2 and vimentin, which are cytoskeleton protein that is generally expressed in normal cells and reorganized after virus infection." (PMID 28079188, 2017).
cancer (42 papers, 2010 to 2025). A tumor composed of atypical neoplastic, often pleomorphic cells that invade other tissues. "We mapped the ACTB and ACTG1 mutations found in these two cancer types on the 3D-structure of actin showing they are in regions important for actin polymer formation or binding to myosin." (PMID 32349449, 2020). "A search in PubMed with the keywords ‘ACTB’ or ‘ACTG1’ and ‘mutations and cancer’ indeed yields a limited number of papers." (PMID 32349449, 2020). "The same might hold true for components of the cytoskeleton, since TUBB, ACTB, and ACTG1 are all included in the candidate gene list, which would be in line with the frequently observed increased expression of cytoskeletal proteins in cancer and associations with poor outcome and chemoresistance." (PMID 40694850, 2025). "Although future studies are needed to determine the role of ACTB and ACTG1 mutations as driver or passenger mutations in different cancers, our data show a possible link between impaired cytoskeletal actomyosin dynamics, cofilin-mediated actin turnover, and cancer development." (PMID 38446501, 2024). "However, experiments are needed to show this causative effect and to rule out the possibility that the observed enrichment of ACTB or ACTG1 mutations in these two cancer types reflect a higher tolerance for such mutations compared to other cancer types in which they are therefore less detected." (PMID 32349449, 2020). "If the two cytoplasmic actin genes ACTB and ACTG1 are more frequently mutated in hematological malignancies than sequencing screens suggest, this should be apparent from a comparison of the alteration frequency of these two genes in blood cancers relative to other cancer types." (PMID 32349449, 2020). "Based on its role in various cancers, ACTG1 is considered a potential biomarker for tumorigenesis and treatment." (PMID 40166371, 2025). "Target prediction and functional annotation identified 59 overlapping genes, with the Proteoglycans in cancer pathways being conserved in both species, mediated by ACTG1, SDC1, FRS2, and WNT9B." (PMID 41296454, 2025). "Many TME-related genes (such as VEGFA, MMP14, CCND1, MAP2K1, SLC2A1) and actin cytoskeleton-associated genes (such as ITGB4, ITGA6, ACTG1, VCL) were downregulated, suggesting a less favorable TME and an altered cytoskeleton network in ISO-treated cancer cells." (PMID 38339062, 2024). "The pan-cancer analysis showed that ACTG1 was highly expressed in most types of cancers, especially STAD." (PMID 38178023, 2024). "In some types of cancer cells, ACTG1 instability can lead to decreased ASAP3 expression, which inhibits cell migration and invasion." (PMID 38077434, 2023). "According to researchers, ACTG1 which is upregulated in cancer, increases the progression of hepatocellular carcinoma." (PMID 37816854, 2023). "It was affirmed elevated ACTG1 in CRC tissues and cells versus normal controls, which further supports the idea that ACTG1 is an oncogene in cancer." (PMID 35349390, 2022). "From observing decreased viability upon gene depletion, we found ACTG1 was a dependency gene in almost a third of the cancer cell lines (n = 254)." (PMID 33217970, 2020). "ARRB2 and JAK3 were highly expressed in T cells, while PTK2 and ACTG1 were mainly enriched in the 'Cancer cluster." (PMID 32549766, 2020). "Notably, only one pathway, Proteoglycans in cancer (p < 0.05), was conserved across both species, with ACTG1, SDC1, FRS2, and WNT9B identified as common genes participating in this pathway." (PMID 41296454, 2025). "Given that the miR-10a/ACTG1 regulatory axis may contribute to the enrichment of the ‘Proteoglycans in Cancer’ pathway, it could play a role in cross-species HCC progression." (PMID 41296454, 2025). "Similarly, ACTG1 encoding Gamma actin provides a structural framework to regulate cell migratory machinery through ROCK signalling and has been implicated in various diseases like cancer." (PMID 41403754, 2025).
cancer (continued). "In the blue module (associated with the untreated cancer cells), the enriched pathways were “Cilium Disassembly”, “Microtubule”, “Tubulin Binding”, “Myosin Binding”, and “Lamellipodium Assembly”, where the genes KIF1C, MAP4, ACTG1, ABLIM3, TRIOBP are involved." (PMID 38534323, 2024). "ACTG1 is involved in cell motility/cytoskeleton maintenance and cancer cell migration." (PMID 31675377, 2019). "ACTG1, SDC1, FRS2, and WNT9B were commonly identified as genes contributing to the enrichment of the ‘Proteoglycans in Cancer’ pathway in both species." (PMID 41296454, 2025). "Results showed that these significantly expressed mtio-ncRNAs mainly enriched the Cancer Gene Neighborhoods pathway, and further analysis of the Cancer Gene Neighborhoods pathway revealed that the main target genes were GCM1 and ACTG1 genes." (PMID 37035732, 2023). "Further analysis revealed that these miRNAs mainly enriched the Cancer Gene Neighborhoods pathway, with GCM1 and ACTG1 as the main target genes." (PMID 37035732, 2023). "Seven target genes, namely DDX5, SOS2, ACTG1, EZR, FN1, HCLS1 and PIK3R5, were involved in proteoglycans in cancer signaling pathway." (PMID 32293320, 2020). "The remaining proteins are involved in the maintenance of the membrane structure (ACTG1 and PTGFRN), the uptake of EVs by endocytosis (CLTC), and the release of exosomes (PKM), in particular from cancer cells." (PMID 32886718, 2020). "Among the actomyosin genes, ACTG1 (cytoplasmic γ-actin) and MYLK2 (skeletal myosin light chain kinase) were consistently amplified or overexpressed across cancers." (PMID 33217970, 2020). "The data indicates that ACTG1 was not a common essential gene that upon gene deletion globally perturbs cancer cell viability." (PMID 33217970, 2020). "Further, while ACTG1 gain was found to be associated with increased PRC2 activity, EZH2, a core member of the PRC2 complex and an oncogenic target in several cancers was not altered in the same patient samples." (PMID 33217970, 2020). "In addition, CCT6A, UTP18, YRDC, RRP12, RFT1, NLE1, as well as DDOST were essential genes across pan-cancer including COAD cells, and ACTG1 and RHOQ were less essential genes in cancer cells." (PMID 31867042, 2019). "Dependency score analysis by DepMap showed that ACTG1 and RHOQ were less essential across pan-cancer cells including COAD cell lines, and CCT6A, UTP18, YRDC, RRP12, RFT1, NLE1, as well as DDOST were essential across pan-cancer cells including most of COAD cell lines." (PMID 31867042, 2019). "The low frequency of ACTB and ACTG1 mutations across all cancers is in part explained because they are not found in many cancer types (ACTB: in 46 out of 75, ACTG1: in 29 out of 75)." (PMID 32349449, 2020).